CD4 (CD4 molecule)
Diseases named in the same sentence as CD4 in open-access papers (continued):
Sharing a sentence is not in itself a finding about the gene and the disease.
tumor (continued). "Treg cells promote immunosuppression by inhibiting immune response to cancer cells, and the expression of CD4+ CD25+ CD127low Tregs had a positive correlation with TGF-β1 and IL-10 expressions and was closely linked to tumor occurrence and development and immunotherapy reactivity." (PMID 35820903, 2022). "Similar analysis of tumor-derived CD4+ T cells revealed six subtypes of CD4+ T cells." (PMID 36028490, 2022). "Also, immune infiltration cells, related to the inhibition of tumor cells, including Macrophage, B cell, CD4 T cell, CD8 T cell, and NK cell, were significantly activated in the AME2 subtype." (PMID 36189258, 2022). "To determine whether IFNγ plays a role in the CD4 T cell–mediated antitumor effect, we treated tumor-bearing mice with Marilyn CD4 T cells in the presence of either αIFNγ or control IgG1 antibodies." (PMID 35903540, 2022). "Increased tumor growth is greater when CD4 T cells are depleted." (PMID 36611875, 2022). "However, there was a lower proportion of HLADR (M1) macrophages (P = 0.0001) and a higher proportion of CD4 T-helper lymphocytes (P = 0.0039) in aggressive tumours with a higher M2:M1 ratio (P = 0.01)." (PMID 35975974, 2022). "Moreover, we found that the CCDC6 levels were positively correlated with the presence of tumor-infiltrating immune cells, including macrophages, CD4+T cells and dendritic cells." (PMID 36186907, 2022). "Most of the infiltrating CD4+ T lymphocytes express CD40L, indicating that activation of CD4+CD40L+ T cells may be the main mechanism leading to the characteristic skin immune damage of DM." (PMID 35711463, 2022). "Several studies have shown that CD4+ T cells are important for tumor immunosurveillance." (PMID 35454882, 2022). "Finally, it has been shown that tumor-derived exosomes are loaded with immunosuppressive molecules that can decrease CD4, CD8 and NK cells." (PMID 35163397, 2022). "An immunoscore based on combined CD4 and FoxP3 intraepithelial expression may serve as an indicator of tumor progression and should be further investigated for its use as a potential prognostic biomarker in OSCC." (PMID 34626165, 2022). "These candidate T cell epitopes could activate CD8+ or CD4+ T cells to induce cytotoxicity for tumor cells." (PMID 35967400, 2022). "The autophagy score was significantly positively correlated with CD4 T immune cells, neutrophils, and macrophages, suggesting that the autophagy score could be used to assess tumor autophagy patterns and immunophenotypes." (PMID 36052243, 2022). "Therefore, to use CD4 T cells as antitumor treatment it would be necessary to ensure that the right effector type of CD4 T cell reaches the tumor site." (PMID 35903540, 2022). "Tumor infiltrating lymphocytes, such as B cells, CD4 positive T helper cells, CD8 positive cytotoxic T lymphocytes and regulatory T cells (Tregs), are communicating and cooperating with other tumor infiltrating immune cells including macrophages, natural killer cells and dendritic cells." (PMID 36159987, 2022). "We unprecedently document that CD4 + T cells are present in primary eBL tumor tissue." (PMID 34668039, 2022). "Interestingly, Scy1 is highly upregulated in the CD4+ cells stimulated by tumour-derived antigens, resulting in induction of a regulatory phenotype of the T cell (Treg), which suggests its potential role in the tolerance mechanism during tumour development." (PMID 36590595, 2022). "Therefore, the interaction between CMTM4 and PD-L1 made a significant impact on tumor microenvironment through targeting CD4 T cells, and then promoted the malignant progression of HCC." (PMID 35986302, 2022). "Several factors could affect apparent number of CD4+ T cells in tumor: recruitment (CXCL9/10), proliferation (IL‐15), and death (IL‐2)." (PMID 34898004, 2022). "Among all CD4+ Th subsets, Th1 cells are responsible for tumor killing by cytotoxic activity." (PMID 35720407, 2022).
tumor (continued). "In concordance with CyTOF data, we observed that among 22 inferred immune cell types by CIBERSORT, the higher cellular fractions of CD4+ T cells, especially the memory CD4+ T cells, and macrophages (M0, M1, M2) eventually increased in tumor sites compared to normal tissues." (PMID 35874784, 2022). "Further studies, perhaps through a modification of our adoptive T cell transfer experiment in tumor-bearing Rag-/- mice using CD4 T cells from perforin/GzmB knockout mice could provide further details on the exact mechanism." (PMID 36569934, 2022). "The described killing effect was achieved with only two injections of CpG+OVA+PTX+CQ-N/A and resulted in the downregulation of PD-L1 in T cells and the induction of CD8+ and CD4+ T cell generation, which are probably the main effector cells for tumor regression and recurrence." (PMID 36303207, 2022). "CD4+ and CD8+ T cells, tumor-associated macrophages, and cells that express immune checkpoint markers, the hierarchy of hematopoietic stem cell differentiation, functional heterogeneity and signaling in T and natural killer (NK) cells have been revealed using the CyTOF platform." (PMID 36376874, 2022). "Based on the TIMER database, the scores of six kinds of infiltrating immune cells related to 33 tumours (B cells, CD4+ T cells, CD8+ T cells, neutrophils, macrophages, and dendritic cells) were calculated, and the correlation of GINS2 expression with these immune cells was analyzed." (PMID 36466552, 2022). "In EBV-associated cancers, Vδ2-T-derived exosomes could significantly suppress tumor growth by inducing CD4+ and CD8+ T cell-mediated antitumor immunity." (PMID 36109501, 2022). "Moreover, cryo-thermal-induced M1 macrophages in early-stage therapy increased the differentiation of CD4+ Th1 subsets, resulting in the formation of long-term antitumor immune protection to inhibit tumor metastasis." (PMID 36389684, 2022). "We found that cDC2/Treg, CD8+ Teff/Treg, and CD4+ Teff/Treg ratios were significantly increased in tumors from mice treated with 7HP349 compared with vehicle, and these ratios were negatively correlated with tumor burden in mice treated with 7HP349." (PMID 35552271, 2022). "We identified nine critical tumor-infiltrating cell types: innate immune cells including macrophages, neutrophils, DCs, and NK cells; adaptive immune cells including B cells, CD4+ T cells, and CD8+ T cells; and sentinel cells including CAFs and endothelial cells." (PMID 35719408, 2022). "However, the combined radioimmunotherapy still greatly inhibited tumor growth after CD4+ T cells depletion." (PMID 35595770, 2022). "If pDCs adopt the pro-tumourigenic phenotype, they can contribute to tumour growth, invasion, and/or angiogenesis stimulation by promoting the differentiation of naïve CD4+ T cells into T cells secreting IL-10, involving immunosuppressive functions, among others." (PMID 35406451, 2022). "CD4+T and B cells are reported to be positively correlated with reduced tumor sizes in PTC." (PMID 36420264, 2022). "First, tumor tissues had high levels of CD4+FOXP3+ Treg cells." (PMID 36483553, 2022). "MHC class II may play a key role in tumor immune surveillance because it can bind a higher diversity of peptides than MHC class I and increase the likelihood of tumor neoantigens being recognized by CD4+ T cells." (PMID 36611830, 2022). "Accumulating evidence suggests that both CD8+ and CD4+ T-cells in the tumor microenvironment (TME) play a crucial role in antitumor immune responses, but also that distinct populations may act as predictive biomarkers for immune checkpoint inhibitors." (PMID 35099641, 2022). "In addition, IL-35 suppresses endogenous antitumor T-cell responses in vivo by reducing CD4+ effector T cells and by increasing Treg cells in the tumor infiltrate." (PMID 35359944, 2022). "We speculate that Gal-9 impairs the function of CD4-positive T cells, which, in turn, may promote tumor growth, migration, and invasion." (PMID 36263183, 2022).
tumor (continued). "Reliable proportions of cancer‐associated fibroblasts (CAFs), macrophages, B cells, CD4/CD8 T cells, endothelial cells, natural killer cells (NK cells), neutrophils, and tumor cells were computed for n = 375, n = 62, and n = 85 patients in TCGA, MDACC, and FHCRC, respectively." (PMID 34382739, 2022). "Metagenomics based on stool samples from cancer patients at the time of diagnosis reveals a correlation between clinical response to immune checkpoint inhibitors and the relative abundance of A. muciniphila recruitment of CCR9 + CXCR3 + CD4 + T lymphocytes into the mouse tumor bed." (PMID 35774450, 2022). "Moreover, serum lipids are observed to enhance the anti-inflammatory effect of neutrophil, the activation of CD8+T cell, and the survival of CD4+T cell, and inhibit tumor progression by strengthening the anti-tumor immune response." (PMID 36421359, 2022). "Many previous studies have shown that immune infiltration-related factors are highly correlated with the prognosis of different tumours, and the number of immune-infiltrating cells, including natural killer (NK) cells, DCs and CD4 T cells, is also highly correlated with tumour prognosis." (PMID 36316684, 2022). "Anti‐OX40 therapy could promote tumor‐infiltrated CD4+ T cells proliferation and reduce the tumor metastasis." (PMID 35474948, 2022). "However, iNOS can also act as a mechanism of M1 macrophage anti-tumor activity, and when expressed in CD4+ T cells can inhibit their differentiation to Treg or Th17 cells." (PMID 35154165, 2022). "In conclusion, CD4+ T cells play an important role in anti-tumor immunity, and dynamic monitoring of CD4+ T cells during immunotherapy could help to evaluate the prognosis of patients and screen for possible patient groups that might particularly benefit." (PMID 35484541, 2022). "From the results, we concluded that the expression of the PD-1 receptor on the CD8+ T lymphocytes in all the tested biological materials, as well as the CD4+ T in the tumor and lymph node samples, significantly correlated with the occurrences of metastases in distant organs." (PMID 35158748, 2022). "Less Treg cells might allow, at least in part, an activation of the endogenous effector CD3+CD8+ and CD3+CD4+ T cells in response to the recognition of tumor specific antigens." (PMID 36077742, 2022). "TA-MSCs are plastic and can be modified by CD4+ T cell to induce tumor growth." (PMID 36324128, 2022). "This review outlines the role of CD4+ T subsets within the tumor microenvironment and summarizes the latest progress regarding their potentials in cancer immunotherapy and methods for improving outcomes in cancer strategies by modulating CD4+ T responses." (PMID 35008422, 2022). "Similarly, preclinical studies have demonstrated the importance of systemic CD4 immunity in immunotherapy efficacy and that CD4+ T cell proliferation is correlated with tumor rejection in murine models." (PMID 35008422, 2022). "In the mice treated with the combination therapy, only the depletion of CD8+ cells abrogated the antitumor effect of the treatment, while the depletion of NK cells exerted a minor effect and depletion of CD4+ T cells had a minimal effect on tumor inhibition by the combination therapy." (PMID 35715953, 2022). "Regulatory T (Treg) and Th17 cells (two subsets of CD4+ cells) in the tumor microenvironment regulate the production of cytokines and chemokines, promote the recruitment and functional activation of immune cell populations, and thus accelerate tumor progression and metastasis." (PMID 36497209, 2022). "Moreover, the key functional cytokines IFN-γ and TNF-α secreting tumor-infiltrating CD3+CD4+ T and CD3+CD8+ T cells increased significantly in the group treated with PMA-TCLV and aPD-L1 combination therapy compared with other groups." (PMID 35217574, 2022).
tumor (continued). "Therefore, in the present research, we focused on live-attenuated Listeria monocytogenes strains as delivery platforms of cancerous antigens, and potent inducers of strong anti-tumor Th1 CD4 and CD8 T cells responses in different solid cancers, as reviewed." (PMID 35173308, 2022). "In addition to directly inducing cancer cell death through catalytic therapy, ChA CQDs activated the tumor immune microenvironment and converted the “cold tumor” to “hot tumor” by recruiting CD4+/CD8+ T cells, macrophages, and NK cells." (PMID 36531332, 2022). "CD4-positive T cell are involved in the tumor immune environment in OS." (PMID 36686663, 2022). "However, PD-1 down-regulates ICOS on CD4+ T cells, which inhibits the differentiation of CD4+ T cells into Th1 cells and affects the anti-tumor response of Th1 cells." (PMID 36119047, 2022). "Group with CD4+IFNγhigh showed smaller tumor weights compared to the group with CD4+IFNγlow cells." (PMID 35651802, 2022). "In the anti-tumor setting, culture of Th9 cells with IL-1β or cells with heightened NF-kB activity exhibited enhanced expression of the CD4 cytotoxic lymphocyte transcription factor Eomes and enhanced granzyme/perforin-associated killing after adoptive transfer." (PMID 36389679, 2022). "Similarly, we found a significant increase of CD4+ Tconv cells and a decrease of Tregs among tumor-infiltrating CD4+ T cells in the NEO cohort, which enhanced the ratio of CD4+ Tconv cells to Tregs." (PMID 36509285, 2022). "Alternatively, TCRs cloned from DP CD4+ TILs reactive against patient-matched tumor (neo)antigens could be used to develop TCR-engineered T cells from the patient’s peripheral blood for adoptive transfer as an interventional therapy." (PMID 35703176, 2022). "CD4+/CD8+ positivity was analyzed in 75 cases in four systematically predefined tumor regions." (PMID 35454849, 2022). "An immunoscore based on combined CD4 and FoxP3 intraepithelial expression may serve as an indicator of advanced tumor progression and should be further investigated for its use as potential prognostic biomarker in OSCC." (PMID 34626165, 2022). "Similarly, our current study indicates that tumor-reactive CD4+ TILs were enriched in the DP CD4+ subset." (PMID 35439168, 2022). "The infiltration of Tfh, Tregs, activated NK cells, and M0 macrophages was significantly increased in high-MISP tumor tissues, while the infiltration of activated CD4+ memory T cells, CD8+ T cells, resting NK cells, monocyte, M2 macrophages and neutrophils was decreased." (PMID 35433491, 2022). "We wondered, therefore, whether tumor-specific CD4 T cells might interact with local TAMs, and reeducate them in vivo to overcome local tumor-derived signals." (PMID 35903540, 2022). "Thus, we generated CAR-T cells armored with IL-7 to prolong the persistence of infused T-cells, particularly CD4 + T cells, and enhanced anti-tumor response." (PMID 35869100, 2022). "Thus, the CD4+T can target tumor cells in various ways, either directly by eliminating tumor cells through the cytolytic mechanism or indirectly by modulating the tumor microenvironment." (PMID 36051923, 2022). "Our data suggest that Trm CD4+ T cells might differentiate into Treg-C3 cells in situ within the immunosuppressive tumor environment." (PMID 34793335, 2022). "have investigated interaction among neutrophils, CD4+ T cells, and tumor cells in the gastric TME." (PMID 36091114, 2022). "Moreover, CD8 and CD4 depletion inhibits the anti-CTLA-4 effect in CT26 subcutaneous models suggesting a primordial role of T cell modulation in the tumor microenvironment as a mechanism of action behind the anti-cancer efficacy of anti-CTLA-4." (PMID 35339889, 2022). "When re-exposure to tumor antigen, CD4+ memory T cells undergo fast expansion and induce more effective and faster immune response against tumor antigen and may prevent tumor relapse." (PMID 35506372, 2022). "cDC2s stimulate CD4+ T cell responses including CD4+ T cell-mediated tumor immunogenicity." (PMID 36275666, 2022).
tumor (continued). "Secondary endpoints defined as tumor tissue infiltration with CD4+, CD8+ T-cells and CD20+ B-cells, lymphocytic response measured through cytokine concentrations (e.g., NFα, IFN-γ, RANTES) and antibody response (e.g., IL-10, IL-6) in patients’ blood, prostate and skin biopsies were positive." (PMID 36428811, 2022). "Interestingly, Treg elimination that was followed by cancer antigen vaccination generated effective anti-tumor CD4+ and CD8+ T-cell responses in cancer patients with advanced malignancies." (PMID 35634292, 2022). "Many studies have observed that anti-VEGF agents promote the accumulation of CD8+ and CD4+ T lymphocytes in tumors, decrease PD-1 expression of tumor-infiltrating T lymphocytes and inhibit regulatory T cells as well as myeloid-derived suppressor cells and their immunosuppressive functions." (PMID 35280787, 2022). "In mice, oral supplementation with A. muciniphila after fecal microbial transplantation (FMT) from non-responders restored the efficacy of PD-1 blockade in an interleukin-12-dependent manner by increasing the recruitment of CCR9+CXCR3+CD4+ T lymphocytes into mouse tumor beds." (PMID 36058945, 2022). "CD4+ T cells and M1 macrophage were correlated with increased anti-tumor response." (PMID 36440228, 2022). "Our studies demonstrated that the LC4-PLG-RGD anti-tumour activity is better than LC4 in vivo, which can infiltrate more CD8+ T cells and CD4+ T cells in tissues, reduce the Treg cell proportion infiltrated by tumour, and weaken the activation ability of T cells in peripheral immune organs." (PMID 36195696, 2022). "Importantly, we demonstrated that certain tumor cell clones and CD4+ Treg subclusters were adaptively selected to evolve the resistant phenotype in response to NACT." (PMID 35907904, 2022). "In other tumor models, CD4+ T cell-derived IFNγ could inhibit tumor angiogenesis by acting directly on tumor cells, which requires tumor responsiveness to IFNγ." (PMID 36159781, 2022). "This is consistent with the results of previous studies, suggesting that CD4(+) T cells in circulating blood may play a central role to evoke an immune response against tumour‐specific antigens induced by CRT." (PMID 35502766, 2022). "Regulatory T (Treg) and T helper 17 (Th17) CD4+ T-cell subsets have emerged as key elements facilitating a pro-tumor inflammation environment that could favor cancer initiation, progression, and metastasis." (PMID 35386705, 2022). "CD4+ T cells play a role in tumor invasion and progression in the tumor microenvironment." (PMID 36225932, 2022). "In the spleen tissues, we found significantly higher percentages of CD4+ and CD8+ T cells in mice treated with combination treatment compared with those that received monotherapy or untreated controls, while tumor-bearing mice had decreased CD4+ T cells (p< 0.05)." (PMID 35992834, 2022). "Studies have revealed that B cells, especially Bregs, could promote tumor progression by inducing resting CD4+ T cells to transform into Tregs in various cancers." (PMID 35241665, 2022). "The increased expression of TNF-α in CD4+ T cells was also compounded with a significant decrease in the expression of inhibitory cytokine TGF-β in the combinatorial treatment of CT26 tumor cells when compared to single agents further confirming the immune stimulation." (PMID 36387154, 2022). "Besides, tumor-reactive CD4+ T cells have been found to ensure efficient effector cytolytic T lymphocytes (CTLs) recruitment at the tumor site." (PMID 35928870, 2022). "However, SI-2 treatment reduced the number of tumor-infiltrating CD4+/Foxp3+ regulatory T (Treg) cells compared to vehicle treatment." (PMID 36316775, 2022). "The remaining cells were nine immune cell populations comprising the tumor immune microenvironment, including B cells (B), CD4 + T cells (CD4), CD8 + T cells (CD8), dendritic cells (DC), granulocytes (Gran), mast cells (Mast), macrophages (Mφ), natural killer cells (NK), and regular T cells (Tregs)." (PMID 35027529, 2022).